ACSL4 (acyl-CoA synthetase long chain family member 4)
Diseases named in the same sentence as ACSL4 in open-access papers (continued):
Sharing a sentence is not in itself a finding about the gene and the disease.
bladder cancer (7 papers, 2021 to 2025). "We utilized NMF dimensionality reduction clustering to identify a novel ferroptosis-related TME cell subpopulation, ACSL4+CAFs, in BCa single-cell transcriptome data, uncovering its involvement in various phenotypes of bladder cancer." (PMID 39238647, 2024). "Mechanistic studies revealed that FLRT2 elevated acyl‐CoA synthetase long‐chain family member 4 (ACSL4) expression, increased lipid peroxidation and subsequently facilitated ferroptosis of human bladder cancer cells." (PMID 37480224, 2023). "FLRT2 overexpression elevated, while FLRT2 silence reduced ACSL4 protein expression in human bladder cancer cells." (PMID 37480224, 2023). "We demonstrate that FLRT2 elevates ACSL4 expression and subsequently facilitates lipid peroxidation and ferroptosis, thereby inhibiting the malignant phenotype of human bladder cancer cells." (PMID 37480224, 2023). "Mechanistic studies revealed that FLRT2 elevated ACSL4 expression, increased lipid peroxidation and subsequently facilitated ferroptosis of human bladder cancer cells." (PMID 37480224, 2023). "In summary, we demonstrate that FLRT2 elevates ACSL4 expression to facilitate lipid peroxidation and subsequently triggers ferroptosis, thereby inhibiting the malignant phenotype of human bladder cancer cells." (PMID 37480224, 2023). "Overall, we demonstrate that FLRT2 suppresses bladder cancer progression through inducing ACSL4‐mediated ferroptosis." (PMID 37480224, 2023). "Leucine-rich repeat transmembrane protein FLRT2 (FC = 8.891, p = 5.15E-03) promotes lipid peroxidation by increasing the expression of acyl-CoA synthetase long-chain family member 4, thereby triggering ferroptosis and inhibiting the malignant phenotype of human bladder cancer cells." (PMID 40709343, 2025). "This study revealed the significant impact of ferroptosis on bladder cancer TME and identified novel ferroptosis-related TME cell subpopulations, ACSL4+CAFs, and important BCa biomarker SDC1." (PMID 39238647, 2024). "This study aimed to explore the role of ACSL4 in CD8+ T cell tumor infiltration and outcomes of bladder cancer (BLCA) patients after immunotherapy." (PMID 34868963, 2021).
breast tumor (7 papers, 2012 to 2023). "In particular, an assessment of ACSL4 protein expression in breast tumor samples is needed to ascertain the utility of this protein as a predictive and prognostic biomarker." (PMID 37306503, 2023). "PADI2 affects tumorigenesis in breast tumor cells by regulating the expression of ACSL4, BINC3 and CA9, which are known to promote abnormal lipid metabolism and cell invasion of tumors." (PMID 27478411, 2016). "To determine the potential relevance of such contamination in evaluating ACSL4 levels, we determined ACSL4 expression levels in normal and stromal tissue utilizing microarray data reported for microdissected breast tumor tissue." (PMID 24155918, 2013). "Therefore, together with phospho-p70S6K, phospho-S6 and phospho-4E-BP1, ACSL4 appears to be a useful predictor of mTOR activity and whether breast tumors will respond to the inhibition of mTOR." (PMID 26536660, 2015). "Further work will be required to demonstrate that routine measurement of ACSL4 in breast tumor samples might obviate the need for hormone/HER2 receptor measurements in cases where ACSL4 is positive, or be useful as a marker, in addition to receptor status, in making treatment decisions." (PMID 24155918, 2013). "Moreover, the study found that PADI2 can regulate ACSL4, BINC3 and CA9 expression to advance abnormal lipid metabolism and cell invasion in breast tumors." (PMID 27478411, 2016). "Importantly, the expression of these genes (except for Acsl4) was not significantly altered in the presence of a low metastatic 4T07 primary breast tumor." (PMID 36732635, 2023).
COVID-19 (7 papers, 2021 to 2026). A disease caused by infection with severe acute respiratory syndrome coronavirus 2. "As an ACSL4 inhibitor, TZDs not only interrupt the oxidation of AA or AdA to reduce the pathological damage caused by COVID-19 but also acts as an insulin sensitizer." (PMID 37303950, 2023). "Drugs that potentiate the GPX4-GSH axis, induce RTA and ACSL4 activity and, finally, cause labile pool iron depletion are likely candidates in COVID-19 treatment." (PMID 34829548, 2021). "One postulated mechanism for the pioglitazone effect on COVID-19 is via inhibition of acyl-coenzyme A synthetase long-chain family member 4 (ACSL4), which is known to regulate an iron-dependent programmed cell death process called ferroptosis." (PMID 39308871, 2024). "It is well known that lipid peroxidation is the most important step in ferroptosis, thus blocking key enzymes (such as ACSL4 and LOX263) of this process as a potential approach for COVID-19 treatment." (PMID 35697684, 2022). "In response to the ferroptosis manifestation of COVID-19, it has been suggested that drugs that enhance the GPX4-GSH axis, induce RTA and ACSL4 activity and ultimately lead to iron depletion in the unstable pool may be candidates for COVID-19 treatment." (PMID 36060261, 2022).
endometrial cancer (7 papers, 2022 to 2026). Primary or metastatic malignant neoplasm involving the endometrium (mucous membrane that lines the endometrial cavity). "In this study, after treatment of AF, the expressions of SLC7A11, GPX4, and FTH1 were upregulated, and the expression of ACSL4 was downregulated, indicating that AF induced the ferroptosis of endometrial carcinoma KLE cells." (PMID 35635082, 2022). "Moreover, the data from The Human Protein Atlas indicate that ACSL1, ACSL4, and ACSL5 are favorable prognostic markers in renal cancer, urothelial cancer, and endometrial cancer." (PMID 38539505, 2024).
myeloma (7 papers, 2016 to 2025). "In that analysis, of all ACSLs, only ACSL4 was shown to be overexpressed in myeloma cells relative to control tissues." (PMID 39853696, 2025). "Analysis of the Multiple Myeloma Research Foundation (MMRF) CoMMpassSM study showed that high ACSL1 and ACSL4 expression in myeloma cells are both associated with worse clinical outcomes for MM patients." (PMID 39853696, 2025). "Meanwhile, knockdown of ACSL4 can inhibit cell proliferation by regulating c-MYC in multiple myeloma." (PMID 39039611, 2024). "Cancer Dependency Map (DepMap) data showed that all five ACSLs have negative Chronos scores, and ACSL3 and ACSL4 were among the top 25% Hallmark Fatty Acid Metabolism genes that support myeloma cell line fitness." (PMID 39853696, 2025). "Thus expression of ACSL4 has been described as a “double-edged” sword in multiple myeloma since it both increases tumor progression and is a requirement for induction of ferroptosis." (PMID 37306503, 2023). "Thus, suppression of ACSL4 may be a key mechanism through which Dp44mT mediates its anti-myeloma effect." (PMID 41442907, 2025). "For the most part, ACSL4 expression is upregulated in cancer when compared with normal tissue, as is observed in the instances of colorectal cancer, hepatocellular carcinoma and multiple myeloma and has been demonstrated to mediate increases in proliferation, migration and invasion in these cancers." (PMID 37306503, 2023). "ACSL1, ACSL3, ACSL4, and ACSL5 are expressed in primary myeloma cells and supportive of myeloma cell fitness, suggesting that broad targeting of the ACSLs could be impactful for MM patients." (PMID 39853696, 2025). "All of the five human ACSL family members had negative Chronos scores (suggesting they support myeloma cell line growth and survival), and ACSL3 and ACSL4 were in the top 25% most essential fatty acid metabolism‐related genes." (PMID 39853696, 2025).
myocardial infarction (7 papers, 2021 to 2025). Gross necrosis of the myocardium, as a result of interruption of the blood supply to the area, as in coronary thrombosis. "Deferoxamine treatment decreased myocardial infarct size and serum CK activity; decreased ACSL4 and MDA levels; upregulation of GPX4." (PMID 37942067, 2023). "ALDH2 deficiency enlarged myocardial infarct size, increased CK-MB, LDH and 4-HNE; iron accumulation; MDA production; glutathione depletion; GPX4 inactivation; increased ACSL4 and TfR1; downregulated FTH1and GPX4." (PMID 37942067, 2023). "In acute myocardial infarction, silencing NEAT1 alleviates disease severity by suppressing ferroptosis via the miR-450 b-5 p/ACSL4 pathway." (PMID 41268533, 2025). "The expression of ACSL4, LAMP2, PTEN, PTGS2, and SAT1 were different in the early and late stages of myocardial infarction." (PMID 36407421, 2022).
renal fibrosis (7 papers, 2023 to 2025). A final common manifestation of a wide variety of chronic kidney diseases characterized by glomerulosclerosis and tubulointerstitial fibrosis. "In this study, we aim to discuss the potential role and underlying mechanism of ACSL4-mediated ferroptosis of tubular epithelial cells (TECs) during renal fibrosis." (PMID 37670055, 2023). "The unbiased gene expression studies showed that ACSL4 expression was tightly associated with decreased renal function and the progression of renal fibrosis." (PMID 37670055, 2023). "Therefore, we suggest that renal fibrosis may be caused by ACSL4-induced incrassation of AA-PE and AdA-PE in membrane phospholipids which are the ferroptotic precursors." (PMID 37670055, 2023). "Furthermore, our data demonstrated a similar upregulation of ACSL4 expression in kidney tissues from patients with CaOx stones, further suggesting that ACSL4 is closely associated with CaOx stone-induced kidney injury and renal fibrosis." (PMID 37893066, 2023). "By the way of immunofluorescence, we found that ACSL4 was highly expressed in the renal tubules of both two renal fibrosis models." (PMID 37670055, 2023). "In our study, pharmacological inhibition of ACSL4 using abemaciclib effectively blocked the development of renal fibrosis following kidney injury in vivo." (PMID 37893066, 2023). "Our study used UUO and FA mouse models treated with ROSI by intraperitoneal injection and sacrificed on days 14 and 28 separately, to determine the role of ACSL4 inhibition in renal fibrosis." (PMID 37670055, 2023). "In vivo and in vitro experiments demonstrated that inhibiting ferroptosis or ACSL4 mitigated calcium oxalate crystal-induced renal fibrosis." (PMID 37893066, 2023). "Further investigation showed that inhibition of ACSL4 obviously attenuates the progression of renal fibrosis by reducing the proferroptotic precursors arachidonic acid- and adrenic acid- containing phosphatidylethanolamine (AA-PE and AdA-PE)." (PMID 37670055, 2023). "In summary, our study suggests that YAP induces cellular ferroptosis and promotes renal fibrosis induced by CaOx crystal through upregulation of ACSL4 expression." (PMID 37893066, 2023). "We employed an ACSL4-specific inhibitor and silenced ACSL4 gene expression to determine the impact on ferroptosis activation and consequently on renal injury and renal fibrosis, both in vivo and in vitro." (PMID 37893066, 2023). "As such, these findings suggest that YAP exacerbates renal fibrosis induced by CaOx crystal deposition by inducing cellular ferroptosis through upregulation of ACSL4 expression." (PMID 37893066, 2023). "In our present study, we developed a mouse model of CaOx kidney stones to investigate the effect of ACSL4 expression and ferroptosis activation on renal fibrosis." (PMID 37893066, 2023). "In conclusion, these results suggest that inhibition of YAP mediates the downregulation of ACSL4 expression, which in turn inhibits CaOx crystal-induced ferroptosis and renal fibrosis." (PMID 37893066, 2023). "Findings from our study revealed that ACSL4, as the lynchpin in the reprogramming of lipid metabolism, aggravates renal fibrosis by activating endogenous ferroptotic mechanisms." (PMID 37670055, 2023). "Vaccarin mitigates renal fibrosis by suppressing ferroptosis through downregulation of ACSL4." (PMID 41288931, 2025). "Downregulation of ACSL4 prevents renal fibrosis by reducing ferroptosis in renal tubular cells." (PMID 41288931, 2025). "Additionally, investigations into renal fibrosis have indicated that downregulating ACSL4 can mitigate TGF-β1-induced ferroptosis and the fibrotic phenotype." (PMID 40001138, 2025). "From this, we inferred that ferroptosis of TECs may be one of the potential mechanisms of renal fibrosis, and inhibition of ferroptosis by targeting ACSL4 may be an effective treatment for alleviating renal fibrosis." (PMID 37670055, 2023).
renal fibrosis (continued). "We had demonstrated that ACSL4 may aggravate kidney fibrosis by promoting ferroptosis and explored how ACSL4 alters the sensitivity to ferroptosis in renal fibrosis by changing the lipid composition of phospholipids of the cell membrane." (PMID 37670055, 2023). "Moreover, YAP silencing suppressed ferroptosis by downregulating ACSL4 expression, thereby attenuating calcium oxalate crystal-induced renal fibrosis." (PMID 37893066, 2023). "Thus, our data suggest that ACSL4-induced ferroptosis plays a facilitative role in the development of CaOx crystal deposition-induced kidney injury and renal fibrosis." (PMID 37893066, 2023). "In conclusion, our results demonstrated the important role of ACSL4 in the ferroptosis of renal fibrosis and showed that inhibiting ACSL4 may reduce the occurrence of ferroptosis in renal fibrosis." (PMID 37670055, 2023). "Subsequently, we explored whether knockdown of ACSL4 could attenuate renal fibrosis via blocking ferroptosis." (PMID 37670055, 2023). "Ferroptosis was clearly evident in IR-induced renal fibrosis but was substantially ameliorated in HDAC4-KO mice, as indicated by decreased ACSL4 expression and restored GPX4 levels." (PMID 41282137, 2025). "Thus, we found that ACSL4 is upregulated in the kidney tissue of CKD through the analysis of the Nephroseq-database and the experiments of renal fibrosis in vivo and vitro, and is also involved in the ferroptosis-related fibrotic kidney." (PMID 37670055, 2023). "A study on renal fibrosis revealed that, after stimulating human renal tubular epithelial cells with calcium oxalate crystals, activated YAP could be translocated to the nucleus to increase the expression of ACSL4 and to aggravate their fibrotic phenotype." (PMID 40867551, 2025).
diabetic retinopathy (6 papers, 2022 to 2025). "AlkB homolog 5 (ALKBH5) has been shown to alleviate diabetic retinopathy by decreasing m6A modification of ACSL4 mRNA, thus attenuating ferroptosis." (PMID 41288931, 2025). "Glia maturation factor-β induces ferroptosis by impairing chaperone-mediated autophagic degradation of ACSL4 in early diabetic retinopathy." (PMID 37600716, 2023). "Elevated glucose levels may promote diabetic retinopathy through ACSL4." (PMID 41288931, 2025). "In diabetic retinopathy, ZFAS1 facilitates endothelial ferroptosis via miR-7-5p/ACSL4 axis." (PMID 39296014, 2024).
inflammatory bowel disease (6 papers, 2021 to 2025). A spectrum of small and large bowel inflammatory diseases of unknown etiology. "In Inflammatory Bowel Disease (IBD), ferroptosis of intestinal epithelial cells caused by dysfunctional GPx4 and heightened ACSL4 protein level damages the mucosal barrier." (PMID 41462611, 2025). "For instance, ACSL4 expression is markedly elevated in inflamed intestinal tissues, correlating with ferroptotic damage in conditions like inflammatory bowel disease." (PMID 40565780, 2025).
lipid metabolism disorder (6 papers, 2021 to 2025). "In this study, seven core genes (Amacr, Cyp39a1, Echs1, Gpd2, Osbpl9, Acsl4, and Mcee) closely associated with lipid metabolism disorders in AP were systematically identified through the integration of bioinformatics and machine learning approaches." (PMID 41007695, 2025). "There are several splice variants of ACSL4 that may be involved in lipid metabolism disorders, adding to the complexity of this enzyme’s regulation and function." (PMID 37372148, 2023). "For example, circRNA_104718 activates ACSL4-mediated lipid metabolic disorder by sponging miR-29b-3p." (PMID 40563332, 2025). "Findings from this study suggest that Acsl4 is not only a central driver of lipid metabolism disorders in AP but also a critical molecular link between metabolic dysregulation and inflammatory cascades." (PMID 41007695, 2025). "Collectively, these results suggest that low expression of miR‐142‐3p contributes to hepatic lipid metabolism disorder through the upregulation of ACSL4." (PMID 39291441, 2024). "Thus, dictamnine inhibits the ACAT1 and FABP-1expression and activates ACSL4 expression, which collectively contributes to lipid metabolism disorder and the progression of hepatotoxicity." (PMID 34595163, 2021). "Besides, the up-regulation of Acyl-CoA synthetase long-chain family member 4 (ACSL4) and down-regulation of acetyl-coa acetyltransferase 1 (ACAT1) and fatty acid binding protein 1 (FABP-1) proteins were linked to lipid metabolism disorder." (PMID 34595163, 2021). "Dictamnine also increased intracellular lipid metabolism disorder via the down-regulation of ACAT1 and FABP-1 and up-regulation of ACSL4." (PMID 34595163, 2021). "At the same time, some studies demonstrated that puerarin could inhibit the expression of ACSL4 and PTGS2 and then reduce lipid peroxidation and regulate lipid metabolism disorder." (PMID 35888777, 2022).
non-small cell lung carcinoma (6 papers, 2021 to 2025). A group of at least three distinct histological types of lung cancer, including non-small cell squamous cell carcinoma, adenocarcinoma, and large cell carcinoma. "For instance, lncRNA NEAT1 regulates ferroptosis sensitivity in non-small-cell lung cancer by interacting with ACSL4 and GPX4." (PMID 39280701, 2024). "Recent study found that the NEAT1 could target binding with ACSL4 and downregulate the expression of ACSL4, resulting in decreased sensitivity of non-small cell lung cancer (NSCLC) cells to ferroptosis." (PMID 35910359, 2022).
osteosarcoma (6 papers, 2021 to 2026). A usually aggressive malignant bone-forming mesenchymal neoplasm, predominantly affecting adolescents and young adults. "They further constructed an ACSL4/GPX4 double-gene knockout (ACSL4−/−/GPX4−/−) human osteosarcoma cell line U2OS." (PMID 36160012, 2022). "Some tumor cell lines (possibly containing drug-resistant osteosarcomas) are also found to be resistant to ferroptosis burst when GPX4 is inhibited along with the acyl-CoA synthetase long-chain family member 4 (ACSL4) expression." (PMID 35402247, 2022). "Furthermore, we employed shRNA targeting ACSL4 to silence ACSL4 to characterize the functional importance of ACSL4 in osteosarcoma cells." (PMID 38564125, 2025).
diabetic cardiomyopathy (5 papers, 2024 to 2026). Diabetic cardiomyopathy is a disorder of the heart muscle in people with diabetes. "Recent studies have demonstrated that ACSL4-dependent ferroptosis signaling contributes significantly to disease progression in diabetic cardiomyopathy, nephropathy, and retinopathy." (PMID 40843317, 2025). "This activation decreases RNA expression of the ferroptosis suppressors SLC7A11 and FTH and increases expression of the ferroptosis promoter long-chain-fatty-acid-CoA ligase 4 (ACSL4), pointing to the involvement of NF-κB and hence ferroptosis in the pathogenesis of diabetic cardiomyopathy." (PMID 39372215, 2024).